IGF1 (insulin like growth factor 1)
Diseases named in the same sentence as IGF1 in open-access papers (continued):
Sharing a sentence is not in itself a finding about the gene and the disease.
neuropathy (14 papers, 2005 to 2026). A disorder affecting the nervous system that manifests with pain, tingling, numbness, and/or muscle weakness. "Specific genes increased in patients withoutlinezolid-associated neuropathy included ATG4C, BAX, and IGF1, while patients onlinezolid who suffered from neuropathy had an increase in AURKB, CASP3, CASP8, CDK1,CDKN1B, CEBPB, NADSYN1, NRF1, GPX7, and SBSN." (PMID 38939039, 2024). "Coadministration of IGF-1 has also shown efficacy in neuropathy induced by the chemotherapy agents (vincristine and taxol) in mice." (PMID 37242543, 2023). "Recombinant IGF-1 promoted acute resolution of hyperalgesia, prevented vincristine-induced neuropathy, and behavioral signs of PDN and reverse neuronal hyperactivity, and elevated nociceptive threshold and its antinociceptive effects." (PMID 37242543, 2023). "Studies show that IGF-1 may promote the resolution of hyperalgesia, prevent chemotherapy-induced neuropathy and behavioral signs of PDN, reverse neuronal hyperactivity, and elevate the nociceptive threshold." (PMID 37242543, 2023). "We found that IGF-1 may have several positive effects on pain management, including promoting the resolution of hyperalgesia, preventing chemotherapy-induced neuropathy, reversing neuronal hyperactivity, and elevating the nociceptive threshold." (PMID 37242543, 2023). "IGF-1 signaling may also mitigate chemotherapy-induced neuropathy (CINP)." (PMID 37242543, 2023). "Previous studies have shown that IGF1 levels are down-regulated in peripheral nerves in diabetic and non-diabetic types of neuropathy." (PMID 26025657, 2015). "To study the role of the IGF1/IGFBP5/IGF1R system for axon maintenance, we investigated alterations of expression of IGFs and IGFBPs in peripheral nerves of patients with DNP and compared them with other neuropathies and healthy controls." (PMID 26025657, 2015).
placental insufficiency (14 papers, 2012 to 2026). Failure of the placenta to deliver an adequate supply of nutrients and oxygen to the fetus. "KEY POINTS: Simultaneous supplementation of oxygen and glucose to fetuses with placental insufficiency successfully increased fetal arterial oxygen, glucose and IGF-1 concentrations." (PMID 41840346, 2026). "We propose that decidual mTORC1 links oxygen availability and IGF-1 signaling to placental insufficiency and impaired fetal growth by regulating IGFBP-1 secretion and phosphorylation." (PMID 34572595, 2021). "In a mouse model of surgically-induced placental insufficiency, we are able to detect expression of human IGF-1 in placenta and maintenance of fetal growth." (PMID 26473479, 2015). "This study demonstrates that a once-weekly intra-amniotic injection of a low dose of IGF-1 increases growth of ovine fetuses with growth-restriction secondary to placental insufficiency." (PMID 22629469, 2012). "Growth restriction is often characterised by defects in IGF-1/Insulin-like Growth Factor 1 Receptor (IGF1R) signalling and placental insufficiency." (PMID 41258474, 2025). "Human studies of IUGR pregnancies show a mixed relationship with IGF1, with some studies reporting higher maternal levels of IGF1 in IUGR pregnancies, suggesting compensatory upregulation in response to placental insufficiency." (PMID 28718809, 2017). "This is the first report of IGF-1 regulation of the GLUT9 isoforms and, in the mouse, may indicate the recruitment of alternative glucose transporters by IGF-1 treatment following placental insufficiency when GLUT1 remains at reduced levels." (PMID 24019972, 2013). "Interestingly, there is staining seen in the fetal mesenchyme in the UABL group which is not present in the sham or Ad-IGF-1 treated animals, suggesting perhaps a different response when other cell types are ‘stressed’ in placental insufficiency." (PMID 24019972, 2013).
pulmonary hypertension (14 papers, 2017 to 2025). Increased pressure within the pulmonary circulation due to lung or heart disorder. "The upregulation of miR-379-5p results in decreased expression of insulin-like growth factor 1 (IGF1), a key regulator of endothelin-1, which plays a role in vascular remodeling associated with pulmonary hypertension." (PMID 40710310, 2025). "This study assesses the utility of early biomarkers-5-hydroxyindoleacetic acid (5-HIAA) and insulin-like growth factor 1 (IGF-1)-for diagnosing and monitoring pulmonary hypertension (PH) in children with congenital heart defects (CHD)." (PMID 38929316, 2024). "Decreased expression of miR-223 results in the upregulation of IGF-1R and enhances IGF-1/IGF-1R signaling that mediates right ventricular hypertrophy in the pathophysiology of pulmonary hypertension." (PMID 33511137, 2020). "The IGF-1 system is known to have a role in vascular pathologies, such as pulmonary arterial hypertension, and IGFBP-1 is one of a family of proteins modulating the effects of IGF-1 on vascular smooth muscle and endothelial cells." (PMID 28624389, 2017). "Additionally, knockdown of IGF1R or IGF-1 activity has previously been shown to ameliorate the effects of chronic hypoxia-induced pulmonary hypertension." (PMID 41132156, 2025). "A transcriptomic study employing clinical samples from patients with pulmonary arterial hypertension (PAH) identified primary glycolysis genes (CASP3, IGF1, CDKN2A, and KARS) associated with PAH through combined analysis of scRNA-seq and bulk transcriptomic data." (PMID 41516041, 2025). "Besides, a previous study demonstrated that IGF1 played an anti-apoptosis effect on PASMCs, thereby promoting the accumulation of PASMCs during pulmonary arterial hypertension." (PMID 35636162, 2022). "Moreover, in the pathophysiology of pulmonary hypertension, hypoxic condition will enhance the IGF-1 secretion from the arterial smooth muscle cells, by which to affect pulmonary vessel remodeling." (PMID 33511137, 2020). "In addition, we quantified mRNA levels of IGF-1 since this growth factor might be a potent mediator of vascular growth responses in settings of pulmonary hypertension." (PMID 30453980, 2018). "Serum IGFBP2 levels, as well as IGF1/2 levels, were measured in two independent PAH cohorts, the Johns Hopkins Pulmonary Hypertension program (JHPH, N = 127), NHLBI PAHBiobank (PAHB, N = 203), and a healthy control cohort (N = 128)." (PMID 33019943, 2020).
somatotropinoma (14 papers, 2016 to 2025). "It is reasonable to believe that the association between somatotropinoma and intestinal microbiota is related to the change in GH/IGF-1 level." (PMID 38027221, 2023). "Some studies show a decrease in thyroid volume, by up to 25%, after normalization of IGF-1, achieved through successful surgical removal of somatotropinoma, or by medical treatment with somatostatin analogs." (PMID 32555993, 2020). "In somatotropinomas, E-cadherin expression correlates positively with GH and IGF-1 secretion and and with somatostatin analogue treatment, and negatively with tumor size and invasiveness." (PMID 29507682, 2018). "Despite the pathogenesis not being entirely known, it has been suggested that high levels of insulin-like growth factor-1 (IGF-1) may play a role in the development and growth of cherry angiomas, making them present in association with a somatotropinoma." (PMID 36428828, 2022). "True silent somatotroph tumors do occur but to be properly classified as such, they must be proven to not cause systemic GH or IGF-1 excess." (PMID 34067494, 2021). "Moreover, a previous study showed that addition of IGF1 (100nM) to primary cultures of somatotropinomas indeed leads to a significant decrease of GH secretion in 5/8 tumors, while increasing the PRL secretion of prolactinomas." (PMID 27267119, 2016). "Placental GH (Growth Hormone) increases from weeks 5–15 with a peak at week 37, stimulating liver IGF1 and inhibiting pituitary GH secreted by normal hypophysis, not by somatotropinoma." (PMID 36359512, 2022).
brain tumor (13 papers, 2003 to 2024). "High circulating glucose levels accelerate brain tumor growth and angiogenesis while also preventing apoptosis through activation of the IGF-1/PI3K/Akt/Hif-1a signalling pathways." (PMID 20412570, 2010). "There is a paucity of literature investigating the tumorigenic effects of the GH/IGF-1 axis on brain tumors and craniophayngiomas, in particular, due to the rarity of this occurrence." (PMID 20864785, 2010). "Based on our results, we propose to retest with GST all CO-GHD patients with organic GHD (brain tumors, congenital anomalies, irradiation to the hypothalamic/pituitary region) with 0, 1, or 2 pituitary hormone defects with IGF-1≥ −2 SDS, and patients with idiopathic GHD with IGF-1 < 0 SDS." (PMID 38913686, 2024). "We used IGF-1 level to diagnose GHD at follow-up, as earlier studies have shown that a low IGF-1 level reliably predicts GHD among survivors of radiotherapy-treated childhood brain tumor." (PMID 36067205, 2022). "Since plasma IGF-1 and glucose are both predictive of CT-2A tumour growth, we suggest that either glucose or IGF-1 may be useful biomarkers for predicting the effects of DR on brain tumour growth and angiogenesis." (PMID 14520474, 2003).
deafness (13 papers, 2010 to 2024). An inherited or acquired condition characterized by the complete loss of the ability to hear from one or both ears. "Some of these disorders (such as S-cone syndrome, and growth retardation with deafness and mental retardation due to IGF1 deficiency) follow autosomal recessive inheritance." (PMID 28106113, 2017). "C-RAF deficiency in humans is associated with deafness in the rare genetic insulin-like growth factor 1 (IGF-1), Noonan and Leopard syndromes." (PMID 25975225, 2015). "Severe syndromic deafness in man is associated with null mutations in IGF1 and also with low levels of IGF-I." (PMID 20111592, 2010). "Adult Igf1−/− mice are animal models for the study of human syndromic deafness; they show altered cochlear projection patterns into abnormally developed auditory neurons along with impaired glutamate uptake in the cochlear nuclei, phenomena that probably reflect disruptions in neuronal circuits." (PMID 30881288, 2019). "Finally, deficiencies in IGF-1 and C-RAF have been implicated in some rare and severe human syndromes with defects that include deafness, such as IGF1 deficit (OMIM #147440), Noonan (NS5; OMIM #611553), and Leopard (LPRD2; OMIM #611554) syndromes." (PMID 25975225, 2015). "Also, IGF1-deficient mice presented profound deafness from 1 month of age onwards, without any obvious worsening of hearing parameters with aging." (PMID 33132846, 2020).
memory impairment (13 papers, 2008 to 2026). "We investigated the effects of treadmill exercise and intranasal insulin on learning and memory impairment and the expression of IGF1, BDNF, and GLUT4 in hypothalamus." (PMID 38987609, 2024). "Salvianolic acid B ameliorates memory impairment in VD rats by increasing the level of insulin-like growth factor-1 (IGF-1) and the expression of P-AKT." (PMID 36742208, 2022). "Future studies are needed to investigate the application of insulin/IGF-1 as it may normalize alcohol-related memory impairments, particularly in males." (PMID 41400881, 2025). "Our study fills this void by identifying a novel astrocyte‐mediated WNT3/IGF‐1 signaling axis in the dorsal DG as a critical mechanistic link between peripheral nerve injury and the concurrent development of nociceptive sensitization and memory impairment." (PMID 41414737, 2025). "As a result, IGF-1 transduction was found to block memory impairment in AD mice, suggesting that enhancing IGF-1 expression in the brain could serve as a potential strategy against neuronal damage and memory loss in AD." (PMID 39200370, 2024). "The authors conclude that if the increase in GH-induced IGF-1 levels is too high memory functions may be impaired, whereas this memory impairment may be halted when IGF-1 levels are decreased." (PMID 29980224, 2018). "Moreover, IGF-1 can prevent hippocampus-dependent memory impairment." (PMID 41301404, 2025).
mood disorder (13 papers, 2015 to 2025). A cognitive disorder a disturbance in which the person's mood is hypothesized to be the main underlying feature. "IGF-1 was proposed as a factor probably involved in the mechanism underlying the observed differences in sex incidence of mood disorders." (PMID 36362131, 2022). "These relationships are being investigated in further studies, which suggest that abnormal IGF-1 activity may be associated with the development of mood disorders." (PMID 34362162, 2021). "Hence, abnormal IGF-1 activity may be associated with the development of mood disorders." (PMID 38919642, 2024). "Therefore, the increase in systemic IGF-1 levels observed in patients with mood disorders may be a compensatory mechanism that enhances the hypothalamic-pituitary-growth promotion axis in response to inadequate brain IGF-1 concentrations." (PMID 38919642, 2024). "Insulin-like growth factor 1 (IGF-1) is a crucial neurotrophin that is produced in the brain and periphery and may play an important role in insomnia and mood disorders." (PMID 37151979, 2023).
pituitary disease (13 papers, 2011 to 2025). "The role of IGF-1 in cardiovascular pathology was firstly observed in studies of the causes of death in patients with pituitary diseases." (PMID 29375617, 2017). "Because lower ACTH, lower cortisol or also lower IGF-1 concentrations are probably results of a more advanced (more severe) pituitary disease, the overall quality of life of these patients is much more impaired than of patients with fewer axes involved." (PMID 39997750, 2025). "While serum IGF-1 levels less than 2 standard deviation (SD) below the age-matched mean, in a well-nourished adult with pituitary disease, is highly suggestive of GHD, it is clear that serum IGF-1 and or IGFBP-3 can be normal in patients with undisputed GHD." (PMID 22899919, 2012). "Still, very low IGF-1 levels warrant this evaluation in order to exclude pituitary disease." (PMID 35407641, 2022).
progeria (13 papers, 2010 to 2024). "Taken together, this evidence suggests that thyroid hormone signalling is implicated in progeria through the regulation of IGF-1 in early postnatal development." (PMID 29883366, 2018). "Mechanistically, genetic studies have pointed to the involvement of several key events, notably DNA damage, particularly in the progeria/progeroid syndromes and activities of the insulin/IGF1/mTOR/FOXO pathway in longevity." (PMID 35531366, 2022). "Many of the abnormalities detected in these mice resemble those previously reported in mouse models of progeria, including low circulating levels of IGF-1." (PMID 29883366, 2018). "Circulating growth hormone is converted into IGF-1 in the liver and persistence of transcription-blocking DNA breaks has been shown to down-regulate IGF-1 in nucleotide excision repair defective progeria rodent models." (PMID 25274775, 2015). "Zmpste24 (−/−) mice, a mouse model of progeria, exhibits dysregulation of somatotropic axis, characterized by high levels of circulating growth hormone (GH) and reductions in insulin-like growth factor-1 (IGF-1)." (PMID 23090008, 2012). "Here, we summarize these observations and discuss the importance of GH/IGF-1 balance in longevity as well as its modulation as a putative therapeutic strategy for the treatment of human progeroid syndromes." (PMID 21212467, 2010). "In both analyses, aging and progeria, IGF1 and CCL2 are among the prioritized ligands." (PMID 36289702, 2022). "When comparing progeria patients and healthy children, IGF1 is also lower expressed." (PMID 36289702, 2022). "Dysregulated mechanistic target of rapamycin (mTOR) and insulin-like growth factor 1 (IGF1) signaling, impaired nutrient sensing, and autophagy are implicated in the pathogenesis of progeroid syndromes, laminopathies, as well as aging in the general population." (PMID 35531366, 2022). "In addition, 14 month‐old SirT7−/− mice had reduced IGF‐1 levels in plasma compared with WT littermates, as has been observed in different human and mouse progeroid syndromes." (PMID 27225932, 2016). "Therefore, it would be of interest whether treatments affecting IGF1 expression influence progeria-related skin abnormalities." (PMID 36289702, 2022). "Studies in mice have shown that reduced levels of Insulin-like Growth Factor-I (IGF1) plays a role in the aging of hematopoietic stem cells, and that IGF1 is regulated by miR-1 in a mouse model of progeria." (PMID 39063098, 2024). "For example, miRNA-1 is upregulated in progeria livers in models and regulates IGF-1/PI3K/AKT/mTOR; miRNA-383 is also upregulated and targets IGF-1 and its receptor." (PMID 37895144, 2023). "When comparing IGF1 expression in nonagenarians and progeria patients, the expression levels show little difference." (PMID 36289702, 2022). "In fibroblasts donated by progeria patients, IGF1 appears to be slightly lower expressed than in nonagenarians." (PMID 36289702, 2022). "IGF1 expression is higher in children compared to nonagenarians and progeria patients." (PMID 36289702, 2022).
Brain atrophy (12 papers, 2017 to 2025). Partial or complete wasting (loss) of brain tissue that was once present. "Lipocalin2 (LCN2), osteopontin (OPN), and insulin-like growth factor 1 (IGF-1) were found to be associated with brain atrophy in a region-specific manner." (PMID 38605086, 2024). "Sorrentino and others studied MEG networks concerning insulin growth factor-1 (IGF-1), which has been suggested as a brain atrophy marker related to the risk of developing AD." (PMID 35733422, 2022). "A major goal of this study was to characterize the early- versus late-stage effects of heavy ethanol consumption on the insulin/IGF-1-Akt-mTOR pathway in relation to brain atrophy." (PMID 40149949, 2025). "Numerous studies have demonstrated that the administration of IGF-1 lessened brain atrophy, brain insulin resistance, apolipoprotein E-related neuropathology, and neurotransmitter secretion." (PMID 38473814, 2024). "Some studies have suggested that IGF-1 enhances neurogenesis in the hippocampus and increases neurovascular structure stability, brain atrophy, spatial learning, and memory ability in the CNS." (PMID 38473814, 2024).
celiac disease (12 papers, 2012 to 2025). An autoimmune genetic disorder with an unknown pattern of inheritance that primarily affects the digestive tract. "One disease (celiac disease), 2 behavioral habits factors (delayed AFS and more years of schooling), and 1 physiologic factor (IGF-1) were protective factors of MOA." (PMID 40994718, 2025).